CLTC (clathrin heavy chain)
Diseases named in the same sentence as CLTC in open-access papers (continued):
Sharing a sentence is not in itself a finding about the gene and the disease.
stomach adenocarcinoma (3 papers, 2022 to 2023). "Our results show that the expression of CLTC is increased in gastric cancer patients, which is of great significance for the treatment of gastric adenocarcinoma and further exploration of CLTC." (PMID 35686089, 2022). "In addition, we found that the expression of ESR1, HDAC1, and CLTC genes in patients with stomach adenocarcinoma may be related to poor prognosis and lower overall survival." (PMID 35686089, 2022). "However, the role of CLTC in gastric adenocarcinoma has not been further studied." (PMID 35686089, 2022).
lymphoma (2 papers, 2011 to 2013). A malignant (clonal) proliferation of B- lymphocytes or T- lymphocytes which involves the lymph nodes, bone marrow and/or extranodal sites. "The infiltrating lymphoma cells were positive for CLTC-ALK, and were isolated for cell line derivation." (PMID 21494621, 2011). "Here we describe the establishment of the first CLTC-ALK positive DLBCL cell line from the bone marrow of a patient with chemotherapy-resistant lymphoma." (PMID 21494621, 2011). "CLTC also forms fusion genes in 25-30% of lymphomas and myofibroblastic tumors." (PMID 23496902, 2013).
pancreatic cancer (2 papers, 2013 to 2017). "Moreover, CLTC, a membrane protein like TMEM30A and its partner P4-ATPase, is expressed in pancreatic cancer cells and tumor blood vessels, being involved in the ubiquitous uptake of a variety of macromolecules, membrane transporters, and adhesion molecules." (PMID 28640862, 2017).
B-cell lymphomas (1 paper, 2012). "Possible candidates are CLTC, involved in gene fusions in B-cell lymphomas and non-small cell lung carcinomas, and RAD51C involved in DNA repair and homologous recombination." (PMID 22719901, 2012).
Cirrhosis (1 paper, 2017). A chronic disorder of the liver in which liver tissue becomes scarred and is partially replaced by regenerative nodules and fibrotic tissue resulting in loss of liver function. "Some other makers have been proposed as useful in the diagnosis of hepatocellular nodule arising in the setting of a cirrhosis: among these, clathrin heavy chain (CHC) and EZH2 were those showing better results." (PMID 28280721, 2017).
colorectal adenocarcinoma (1 paper, 2016). The most common type of colorectal carcinoma. "Human colorectal adenocarcinoma (Caco-2) cells were transduced with non-targeting shRNA (ctrl shRNA) and shRNAs (sh489 and sh887) targeting two different sequences in the clathrin heavy chain (CHC)." (PMID 27942025, 2016).
colorectal cancer (1 paper, 2023). A primary or metastatic malignant neoplasm that affects the colon or rectum. "Moreover, 3/4 driver-downregulated genes showed at least weak evidence of TSG role in the matched tissue (MED12 in brain, SF3B4 in breast, and CBLB in colorectal cancer), with the remaining 1 gene being classified as CGC TSG (CLTC)." (PMID 36625266, 2023).
cyst (1 paper, 2017). A sac-like closed membranous structure that may be empty or contain fluid or amorphous material. "Clathrin heavy chain is also highly expressed in the mature cyst." (PMID 28993644, 2017).
diabetes mellitus (1 paper, 2023). A metabolic disorder characterized by abnormally high blood sugar levels due to diminished production of insulin or insulin resistance/desensitization. "We identified novel targets including CLTC (clathrin heavy chain), TNS2, PLCG1 and NIFK (nucleolar protein interacting with the FHA domain of MKI67) for specific therapy of diabetes mellitus and obesity." (PMID 36837510, 2023).
Dravet syndrome (1 paper, 2022). "Reduced dopamine transporter (DAT)‐binding was seen in the majority of the 39 GNDs with available dopaminergic imaging results, but not in Rett syndrome, Dravet syndrome (SCN1A), dihydropteridine reductase deficiency, and CLTC." (PMID 36699000, 2022).
glioma (1 paper, 2023). A benign or malignant brain and spinal cord tumor that arises from glial cells (astrocytes, oligodendrocytes, ependymal cells). "In this study, we found that heparan sulfate proteoglycan 2 (perlecan) (HSPG2), syndecan-1 (SCD1), clathrin (CLTC), and dynamin (DNM1) were present in all patient-derived glioma cells." (PMID 36992317, 2023).
haemorrhoid (1 paper, 2020). "However, the results showed that the expression levels of all important node genes (CLTA, CLTC, RAB3A, SNAP25, SYT1, VAMP2) on Synaptic vesicle cycle pathways from haemorrhoid patient samples were lower significantly than them from healthy tissue samples." (PMID 32620169, 2020).
Hepatic steatosis (1 paper, 2024). Steatosis is a term used to denote lipid accumulation within hepatocytes. "Altogether, Zbtb18 transcriptionally activates the FXR-mediated FAO and CLTC expression, which inhibits NLRP3 inflammasome’s activity alleviating inflammatory stress and insulin resistance, representing an attractive remedy for hepatic steatosis and fibrosis." (PMID 38263084, 2024).
Histiocytosis (1 paper, 2025). An excessive number of histiocytes (tissue macrophages). "KIF5B has been shown to be the most common fusion-partner gene in ALK-positive histiocytosis, whereas CLTC, TPM3, EML4, and TFG have only been infrequently recorded." (PMID 40700600, 2025).
liver fibrosis (1 paper, 2024). "Consistently, we noted specific upregulation of genes enriched in ALK signaling in aged Myof (CLTC, RPS6, STAT3, etc.), which is studied extensively in liver fibrosis." (PMID 37378670, 2024).
lung diseases (1 paper, 2022). "To date, there is no relevant research that reported clathrin 1 gene (CLTC) is associated with lung diseases." (PMID 35859795, 2022).
rheumatoid arthritis (1 paper, 2023). A chronic, systemic autoimmune disorder characterized by inflammation in the synovial membranes and articular surfaces. "CLTC is involved in bone loss in rheumatoid arthritis and is important in osteoclastic progenitor cell fusion." (PMID 37923747, 2023).
cancer (20 papers, 2012 to 2025). A tumor composed of atypical neoplastic, often pleomorphic cells that invade other tissues. "Endocytosis inhibitors such as Wortmannin40 and siRNA targeting clathrin heavy chain significantly reduced HFt transfer, suggesting a role for endocytosis in cancer cell uptake of vesicle-associated HFt." (PMID 39900573, 2025). "Here, we report a patient with a high-grade malignant neoplasm, most compatible with carcinoma, involving the lung and mediastinum in which we identify a novel CLTC::RPS6KB1 fusion as the likely driver mutation." (PMID 40091373, 2025). "The first eight of the nineteen targets, PIAS3, p27, RAB10, DBF4, DUSP14, RBPMS, PDPN and CLTC, were considered to be closely associated with cancer progression after a literature review." (PMID 28120918, 2017). "A panel of Clathrin Heavy Chain (CLTC), Ezrin (EZR), Talin-1 (TLN1), Adenylyl cyclase-associated protein 1 (CAP1), and Moesin (MSN) positive exosomes demonstrated 0.94–0.99 accuracy against other cancers." (PMID 40363817, 2025). "In cancer research, CLTC has also been reported to be involved in tumorigenesis." (PMID 35686089, 2022). "In cancer research, CLTC has also been reported to correlate with tumorigenesis." (PMID 34185412, 2021). "This affected 17/333 pathway-associated genes including six known cancer genes (HNRNPA2B1, STAG2, TCF7L2, SUZ12, CLTC, and ZNF521), Thus, the integration procedure prioritized specific pathway-related genes compared to their original rankings in individual mutation datasets." (PMID 32024846, 2020). "Furthermore, the expression of SLC2A1, CTNNB1, ACTB, and CLTC were significantly changed in only one type of cancer during migration." (PMID 28640862, 2017). "Another 6 genes, SUB1, SLC2A1, CTNNB1, ACTB, HSP90B1, and CLTC were selected from the remaining unknown migration-related genes in order to confirm their relationship with cancer cell migration." (PMID 28640862, 2017). "We discovered novel gene rearrangements in diverse human cancer types, including fusions of ROS1, SLC1A2, RAF1, EWSR1, CDK6, and CLTC." (PMID 23637631, 2013). "Some of these genes have been previously identified as playing a role in tumorigenesis or cancer progression including, WHSC1L1, CLTC, HSF1, and LSM1." (PMID 22719901, 2012). "The CLTC immunoreactivity was significantly higher in carcinomas compared to the non-neoplastic mammary glands (P = 0.018 by a Wilcoxon signed rank test)." (PMID 25560734, 2015). "We identified new gene fusions involving ROS1, SLC1A2, RAF1, EWSR1, CDK6, and CLTC, some occurring in cancer types not previously known to harbor fusions." (PMID 23637631, 2013).
infection (17 papers, 2009 to 2025). The state of being infected such as from the introduction of a foreign agent such as serum, vaccine, antigenic substance or organism. "Both siRNAs downregulating clathrin-mediated endocytosis-associated proteins, such as clathrin heavy chain (CLTC) and Dynamin 2 (DNM2), and agents affecting this uptake pathway (Chlopro, Dynasore, Dyngo-4a) were capable of inhibiting infection with MHV." (PMID 25375324, 2014). "Message for clathrin heavy chain was seen to be significantly reduced for all transfections, with the greatest signal reduction being seen on day 3 post infection and for siCHC3 and siCHC5." (PMID 19272179, 2009). "In addition, BPIV3 infection was inhibited by pretreatment with dynasore or chlorpromazine (CPZ) or knockdown of dynamin II or clathrin heavy chain." (PMID 34072688, 2021). "HeLa cells were infected and stained for clathrin heavy chain 72 h after infection." (PMID 28002452, 2016). "In our study, we investigated the impact of Meth O on the expression of caveolin-1, clathrin heavy chain (CHC), and dynamin-2 in MDBK cells during early infection of BoHV-1." (PMID 39104584, 2024). "In a different approach, we analyzed the effect of silencing the expression of clathrin heavy chain (Chc) on ASFV uptake and infection." (PMID 27110717, 2016). "Taken together with the effect of clathrin heavy chain, dynamin-1, or Eps15 siRNAs on HMPV infectivity, these data indicate that CME of HMPV during entry leads to productive infection of human bronchial epithelial cells." (PMID 26629703, 2015). "Then, we performed SFTSV infection using this cell line and RT-PCR to detect SFTSV RNA in the infected cells, and the result showed that the knockdown of CLTC protein can still lead to a significant decrease of SFTSV infection at 24h, 36h and 48h post infection." (PMID 37624798, 2023). "To examine the roles of clathrin-dependent endocytic pathway in the enhancement of EV71-infection by CPZ, we performed siRNA knockdown of the AP2M1, CLTC, DNM2 and FCHO2 (the reported crucial CME components) in A549 and RD cells and tested the viral infectivity with additional CPZ treatment." (PMID 29298696, 2018). "Thus, while Eps15, dynamin-1, dynamin-2, dynamin-3, and clathrin heavy chain siRNAs inhibited HMPV entry and diminished infection, cells that did become infected exhibited normal amounts of surface F protein." (PMID 26629703, 2015). "Therefore, we, for the first time, using cell model with CLTC protein deletion, confirmed that CLTC protein deletion did not completely block SFTSV infection." (PMID 37624798, 2023). "Furthermore, this research verified that SFTSV infection was significantly inhibited, but not completely blocked, due to the deletion of CLTC protein." (PMID 37624798, 2023). "However, we cannot rule out the possibility of delayed infection in CLTC-KO cells rather than a reduction in infection." (PMID 37624798, 2023).
tumor (15 papers, 2007 to 2025). "DFFA gene associated with sensitivity or resistance of curcumin in tumor cells and treatment with curcumin was able to significantly increase the levels of CLTC mRNA in curcumin treated cells compared with control." (PMID 36440278, 2022). "Considering that CLTC regulates lipid metabolism, which is crucially linked to tumor progression, we therefore further explored whether CLTC could modulate the tumor progression." (PMID 39850878, 2024). "In comparison to the sh-NC group, mice in the sh-CLTC group exhibited significantly lower tumor volume and weight, suggesting that CLTC knockdown effectively inhibited tumor growth." (PMID 39850878, 2024). "CLTC, which is upregulated in tumor tissues, promotes tumorigenesis by altering the cellular response to TGF-β and is considered a potential biomarker for assessing prognosis and treatment efficacy in HCC." (PMID 39850878, 2024). "The CLTC–ALK fusion gene has been shown to be an ALK activator in large B-cell lymphoma and is associated with tumor recurrence." (PMID 35686089, 2022). "A great deal of evidence supports the concept that CLTC fusion protein is involved in tumorigenesis and tumor progression." (PMID 35686089, 2022). "Taken together, these findings revealed that CLTC played a pro‐tumor function by the TGF‐β and AKT/mTOR signaling pathways." (PMID 34185412, 2021). "In particular, we found that TMEM30A regulates several migration-related genes including SUB1, SLC2A1, CTNNB1, ACTB, and CLTC during tumor migration, which further demonstrates the effectiveness of our proposed method." (PMID 28640862, 2017). "Clathrin heavy chain has been shown to promote tumor growth and hypoxia-induced angiogenesis by stabilizing hypoxia-inducible factor 1α and increasing vascular endothelial growth factor signaling." (PMID 25560734, 2015). "Therapeutic vaccination with the mutated CLTC peptide, polyI:C, and α-PD-1 significantly reduces both the frequency and total number of NeoAg-specific Tregs in both the tdLN and TME 18 days after tumor inoculation." (PMID 40196575, 2025). "Moreover, CLTC expression was more highly enriched in HCC tumor samples than in the corresponding normal tissues." (PMID 39850878, 2024). "Importantly, overexpression of TFG rescued both the tumor‐suppressive effect and inhibition of the TGF‐β and AKT/mTOR pathways caused by CLTC down‐regulation, which indicated that the activity of CLTC was TFG‐dependent." (PMID 34185412, 2021). "Down‐regulation of CLTC resulted in tumor‐suppressive effects in vitro and in vivo." (PMID 34185412, 2021). "Moreover, overexpression of TFG rescued the tumor‐suppressive effect and inhibition of the TGF‐β and AKT/mTOR signaling pathways caused by the down‐regulation of CLTC." (PMID 34185412, 2021). "The expression of the CLTC-ALK fusion could be demonstrated by RT-PCR in both the primary tumor and in the LM1 cell line." (PMID 21494621, 2011). "Notably, validation experiments suggested that CLTC could regulate lipid metabolism through R-loop formation and facilitate tumor progression in HCC." (PMID 39850878, 2024). "The CLTC–ALK fusion gene has been confirmed to be an ALK activator in large B‐cell lymphoma and is related to tumor recurrence." (PMID 34185412, 2021). "Notably, we discovered that CLTC, a crucial RLRG, was significantly upregulated in HCC, modulated R-loop-mediated lipid metabolism, and facilitated tumor progression." (PMID 39850878, 2024). "Importantly, we found that CLTC, a key RLRG, regulated lipid metabolism by influencing R-loop formation and facilitated tumor progression in HCC." (PMID 39850878, 2024). "On a mechanistic level, knockdown of CLTC and TFG could block the activation of ER stress and suppress their pro‐tumor function." (PMID 34185412, 2021). "Numerous evidences support the concept that CLTC fusion proteins are involved in oncogenesis and tumor progression; however, the role of CLTC itself has not been studied in depth." (PMID 34185412, 2021).
tumor (continued). "To test whether these tumor‐suppressive effects were not attributed to the loss of clathrin function, we knocked down the expression of CLTCL1, which is another isoform of clathrin heavy chain." (PMID 34185412, 2021). "In addition, the Kaplan–Meier survival assay showed that the patients with positive CLTC expression had a shorter tumor‐free and overall survival than the patients with negative CLTC expression." (PMID 34185412, 2021).
CLTC also shares sentences with these, for which no sentence is quoted: Alzheimer disease (2 papers); autism (2); epilepsy (2); hepatocellular carcinoma (2); inflammatory myofibroblastic tumor (2); renal carcinoma (2); virus infection (2); amyotrophic lateral sclerosis (1); anaplastic astrocytoma (1); anaplastic large cell lymphoma (1); angiosarcoma (1); autosomal dominant mental retardation (1); cardiotoxicity (1); ciliopathies (1); clear cell renal cell carcinoma (1); dengue (1); developmental and epileptic encephalopathy (1); developmental delay (1); diffuse large B-cell lymphoma (1); gastric cancer (1); genetic disease (1); glioblastoma (1); Insulin resistance (1); leukemia (1); liver cancer (1); lumbago (1); melanoma (1); microcephaly (1); movement disorder (1); multiple myeloma (1).
A further 12 diseases each share a sentence with CLTC in 1 paper.